TNF (tumor necrosis factor)
Diseases named in the same sentence as TNF in open-access papers (continued):
Sharing a sentence is not in itself a finding about the gene and the disease.
cancer (continued). "Overexpression of inflammatory cytokines, such as IL-6, TGF-β, and TNF-α can trigger or inhibit cancer development." (PMID 41614883, 2025). "TNF-α inhibitors, including biologics repurposed from autoimmune indications, have already entered clinical testing in cancer patients, either alone or in combination with chemotherapy or immunotherapy." (PMID 40430573, 2025). "On one hand, TNF acts as an effector molecule in CD8+ T‐cell–triggered cell death of cancer cells and serves as a costimulatory cytokine able to enhance naive CD8+ T‐cell proliferation and cytokine secretion." (PMID 40297580, 2025). "Specifically, cytokines like TNF-α, IL-6, IL-18, IL-1β, and INF-γ are implicated in cancer cachexia, promoting elevated energy expenditure, reduced appetite, and skeletal muscle degradation." (PMID 39996717, 2025). "Genetic interaction screening demonstrated RIPK1 regulates the TNF signalling pathway via NF-κB in cancer cells and plays a critical role in modulating cell death." (PMID 41334873, 2025). "Taken together, the TNF/IL-17 signaling axis is involved in creating an immunosuppressive microenvironment that promotes immune evasion by cancer cells." (PMID 40141200, 2025). "IFNγ and TNFα have been previously explored in clinical trials for cancer therapy due to their potent immune-stimulatory effects." (PMID 40547518, 2025). "Increased TNF-α levels disrupt the intestinal immune barrier while also promoting stem cell formation of Dclk1+ tuft cells, which serve as cancer cell lineages." (PMID 41515203, 2025). "Under particular conditions, TNF-α promotes apoptosis in cancer cells via the activation of caspase-dependent pathways." (PMID 40430212, 2025). "TNF serves as a critical factor in apoptosis and cancer and it was the first biosensor fabricated to detect TNF in cancer patients." (PMID 40558454, 2025). "TNF-α plays a role in promoting cell necrosis, which in turn reinforces cancer progression by releasing cell content and debris." (PMID 40710006, 2025). "This review systematically examines the bidirectional relationship between MDD and cancer, establishing chronic inflammation—orchestrated primarily by IL - 6, TNF-α, and IL - 1β—as a critical biological link." (PMID 41000397, 2025). "Many studies tried to evaluate the correlation between cytokines and the pathogenesis of various cancer types and IL-2, IL-6, IL-10, and TNF-α are often target of these analyses." (PMID 40869161, 2025). "It has been revealed that NK cells are the main immune effector, which can mediate differentiation of different cancer stem cells through lysis and secretion of interferon γ and tumor necrosis factor α." (PMID 40552073, 2025). "Multiple studies support that miR-146a influences the expression of genes involved in cancer progression and metastasis by modulating key signaling pathways, including TNFα/TRAF6, IFNγ/STAT, GPCR, PI3K-AKT-mTOR, and TGFβ/SMAD." (PMID 40277937, 2025). "A meta-analysis examining serum inflammatory biomarkers following vitamin D supplementation in cancer patients revealed significant reductions in TNF-α, IL-6, and C-reactive protein (CRP) levels, while IL-10 levels remained unchanged." (PMID 39582404, 2025). "Interleukin-6 (IL-6) collaborates with TNF-α or acts independently to mediate systemic inflammation in cancer cachexia." (PMID 40519290, 2025). "Cancer serum was incubated with control IgG or neutralizing antibodies targeting IL-6, G-CSF, TNFα, and IFNγ before injection into MDX mice." (PMID 41322654, 2025). "In vivo studies demonstrated that TNF-α-loaded exosome-based vehicle delivery enhanced cancer targeting under an external magnetic field, leading to enhanced antitumor efficacy and reduced systemic toxicity." (PMID 41254732, 2025). "P-PI3K, P-AKT, and P-MTOR proteins were primarily localized in the cytoplasm/membrane, while TNF-α was expressed in keratinocytes, infiltrating inflammatory cells (e.g., macrophages, lymphocytes), and some cancer cells." (PMID 41415031, 2025).
cancer (continued). "Elevated circulating HMGB1 and TNF-α levels have been reported in cachectic cancer patients, correlating with skeletal muscle sarcopenia." (PMID 41003013, 2025). "This contrasted with increasing GBRs, where a robust GO signature for inflammation involving NF-κB, TNFα, and IL-17 signaling, plus terms for cancer, was prominent." (PMID 41488369, 2025). "A previous study on other types of cancer has shown that melittin suppressed tumor necrosis factor (TNF)-induced MMP-9 activity by inhibiting the phosphorylation of p38 and ERK1/2 in human aortic smooth muscle cells." (PMID 40141020, 2025). "In CAR-T cell therapy, PE is used to remove inflammatory cytokines, such as IL-6, TNF-α and other molecular cytokines that are released after the interaction between cancer cells and CAR-T cells." (PMID 40630950, 2025). "Tregs exist in two functional states: TNF‐producing Tregs, which are expanded in mouse models of chronic inflammation and cancer, and TNFR2‐expressing Tregs, which dominate and transmit their phenotype to TNF+ Tregs." (PMID 40977146, 2025). "This also indicates that TNF EVs promote not only migration but also structural changes that support the transition of cancer cells to a more aggressive phenotype." (PMID 40567500, 2025). "The dysregulation of pro-inflammatory cytokines, such as tumor necrosis factor-alpha (TNF-α) and interleukins (ILs), has been linked to various diseases, including inflammation, cancer, and autoimmune disorders." (PMID 41011198, 2025). "The Th1 subset exhibits direct cytotoxicity against cancer cells through the production of interferon gamma and tumor necrosis factor alpha (TNF-α)." (PMID 40070843, 2025). "Key pathways included those related to the cell cycle, human T-cell leukemia virus 1 infection, TNF signaling, apoptosis, and proteoglycans in cancer." (PMID 41262126, 2025). "TNF-α, IL-6, and INF-γ have been implicated as mediators of the metabolic changes associated with cancer cachexia." (PMID 40430444, 2025). "Proinflammatory cytokines such as TNFα and IL1β activates the canonical pathway resulting in expression of anti-apoptotic genes promoting tumor survival and progression of cancer." (PMID 41459064, 2025). "The core bioactive compounds include bergapten and β-sitosterol, which are involved primarily in signaling pathways such as pathways in cancer, IL-17 and TNF." (PMID 41311487, 2025). "GBM, a low-prognosis cancer, has been treated with various therapies, including targeting tumor necrosis factor (TNF) to enhance the survival, well-being, and overall health of GBM patient." (PMID 40922752, 2025). "For instance, in adults, TNF-α, produced by immune cells such as lymphoid and macrophage populations, can inhibit T-cell response and activation of cancer cytotoxic T-call activation through interactions with its receptor TNFRSF1B (TNFR2)." (PMID 39796780, 2025). "Cancer cachexia is often accompanied by elevated circulating cytokines like IL-6, IL-1β, and TNF-α as well as acute-phase reactants (CRP, fibrinogen) in patients, resulting in a state of chronic systemic inflammation." (PMID 40572244, 2025). "Early studies indicated that TGFβ and TNF were critical factors responsible for inflammatory microenvironment construction in malignant tumors and were also involved in a variety of cellular processes, including proliferation, motility, and apoptosis." (PMID 40873563, 2025).
cancer (continued). "One of the mechanisms described for the anti-cancer effect of GB is reactive oxygen species (ROS) suppression in cancerous cells, as well as inflammatory cytokines such as TNF-α, IL-6, iNOS, and COX-2." (PMID 41226786, 2025). "A study investigating the relationship of serum levels of TNF-α with survival and progression of cancer in CRC patients produced significant results." (PMID 40558596, 2025). "Among the top 20 KEGG pathways in the S. aureus-positive group are immune and disease pathways such as NF-κB signaling pathway, Chemokine signaling, JAK-STAT signaling, Cancer pathways, and TNF signaling, among others." (PMID 40936092, 2025). "They secrete factors such as IL-17a, TGF-β and TNF-α, as well as NETs, which facilitate the epithelial-mesenchymal transition in cancer cells." (PMID 40050933, 2025). "Cancer tissue has higher levels of the powerful inflammatory cytokine tumor necrosis factor alpha (TNF-α) and promotes cancer." (PMID 41476448, 2025). "KEGG analysis revealed enrichment in pathways related to cancer, mitogen-activated protein kinases (MAPKs), TNF signaling, and the cell cycle." (PMID 39900822, 2025). "Chronic diseases such as COPD, CHF, CKD, cancer cachexia and aging are often characterized by low‐grade systemic inflammation, with elevated IL‐1β and TNF‐α." (PMID 41292279, 2025). "We found that transcriptional misregulation in cancer, pathways in cancer, TNF signaling, PI3K − Akt signaling, efferocytosis, NF − kappa B signaling were the most highly enriched pathways." (PMID 41208649, 2025). "Monotherapy with immunomodulators (HR 188.09, 95% CI 58.7–601.9), anti-TNFα (HR 4.14, 95% CI 1.5–10.8), and UST (HR 3.32, 95% CI 1.1–9.7) similarly exhibited a positive association with cancer risk." (PMID 40361323, 2025). "IFN-γ induces systemic inflammatory responses by increasing the levels of IL-6 and TNF-α, which lead to changes in energy metabolism and neural function, resulting in fatigue symptoms in cancer patients." (PMID 39980555, 2025). "Inflammation is a critical mechanism in the development of cancer-related fatigue, and TNF-α plays a vital role in the development and exacerbation of the syndrome." (PMID 39980555, 2025). "Additionally, pro-inflammatory cytokines in saliva, including IL-1β, IL-2, IL-6, and tumor necrosis factor-alpha (TNF-alpha), are associated with the severity of oral mucosal tissue damage in cancer patients and may serve as early markers for graft-versus-host disease." (PMID 39958008, 2025). "The relationship between TNF inhibitor therapy and cancer development in Asian patients with AS remains insufficiently studied." (PMID 41302997, 2025). "M1 macrophages are typically activated by IFN‐γ or tumor necrosis factor (TNF) and are capable of producing nitric oxide and reactive oxygen species (ROS), which exert cytotoxic effects on cancer cells." (PMID 40530896, 2025). "Our findings indicated that HuTCR-T1 γδ T cells produced higher levels of IFN-γ and TNF-α compared to WT γδ T cells across most tested cancer cell lines and tissues." (PMID 40801630, 2025). "Preliminary knockdown studies using flow cytometry to evaluate the effects of anti-TNF-α siRNA delivery confirmed the safety of the FAuNCs in non-cancer cells and showed selective inhibition of MDA-MB-231 cell growth." (PMID 41439881, 2025). "At the molecular level, this phenomenon is intricately linked to TNF’s ability to activate STAT3-NF-κB signaling pathways, which enhance cancer cell growth and dissemination." (PMID 39980561, 2025). "Cancer cells also secrete proinflammatory cytokines, such as interleukin-1 beta (IL-1β), tumor necrosis factor-alpha (TNF-α), and vascular endothelial growth factor (VEGF), which foment a pro-thrombotic environment in the blood." (PMID 41040779, 2025). "This pattern is in agreement with other studies that have noted higher TNF-α expression in more advanced cancers." (PMID 40299527, 2025).
cancer (continued). "In this randomized, open-label, noninferiority trial, Ytterberg and colleagues demonstrated that the incidence of cancer was higher among patients exposed to tofacitinib compared to those receiving TNF-α inhibitors, with an HR of 1.48 (95% CI: 1.04–2.09)." (PMID 40227584, 2025). "This understanding lends biological plausibility to using TNF-α as a marker of aggressive disease: it is not only a correlate but likely an active participant in the cancer’s behavior." (PMID 40299527, 2025). "Further studies have found that the activation of PLK1 inhibits the expression of TNF-induced cyclin D1, providing a potential mechanism for TNF-α’s involvement in inflammation-induced cancer." (PMID 40612941, 2025). "In the context of cancer cachexia, NF‐κB inhibits MyoD expression at the transcriptional level following TNF‐α activation." (PMID 39764565, 2025). "Protti and collaborators first demonstrated that human pancreatic cancer [pancreatic ductal adenocarcinoma (PDAC)]-derived TNF-α and IL-1 induced the release of TSLP from cancer-associated fibroblasts (CAFs)." (PMID 40873585, 2025). "KEGG pathway analysis highlighted “MAPK signaling,” “TNF signaling,” and “Proteoglycans in cancer” as relevant PDAC pathways." (PMID 40781158, 2025). "A large‐scale study on cancer survivors showed that systemic inflammatory markers (e.g., IL‐1α, IL‐1β, IL‐2, IL‐4, IL‐6, IL‐8, IL‐10, TNF‐α, and C‐reactive protein) are closely related to physical, emotional, and cognitive CRF." (PMID 40095296, 2025). "The serum IL‐6 and TNF‐α level in the LJFE‐treated group was significantly lower than that in the cancer cachexia group." (PMID 40672545, 2025). "Leptin also induces lymphocyte Treg differentiation and increases secretion of pro-inflammatory interleukin 6 (IL-6) and tumor necrosis factor α (TNF-α) by monocytes, which is crucial for cancer progression." (PMID 40076482, 2025). "The levels of cytokines, such as IL-6 and TNF-α, are elevated, stimulating cell cycle progression and preventing apoptosis, thereby allowing cancer cells to proliferate uncontrollably." (PMID 40255569, 2025). "The data available on the use of TNF-α antagonists in patients with a prior history of cancer are primarily derived from retrospective studies." (PMID 40227584, 2025). "These correlated nano mechanoelectrical datasets establish a comprehensive mechanism linking TNF-α to calcium influx exacerbation, providing transformative insights for targeted cancer therapy development." (PMID 41415204, 2025). "A study examined the associations between circulating levels of the inflammatory markers IL-6, C-reactive protein (CRP), and TNF-α with overall cancer incidence as well as the incidence of cancers specific to certain sites (breast and prostate)." (PMID 40584290, 2025). "Cancer prevention properties of the effective extracts and their active compounds were evaluated by measuring the levels of tumor necrosis factor-alpha (TNF-α), interleukin-2 (IL-2), and nitric oxide (NO) using commercial kits." (PMID 40022126, 2025). "We observed that MyD88, p-ERK, p-NF-kB, TNF-α, IL-1β, and IL-6 were significantly suppressed in cancer cells treated with SsnB compared to the control groups." (PMID 40143078, 2025). "Conversely, skimmianine-mediated TNF-α suppression reduced cancer progression, yet TNF-α-associated hub proteins (TNF-α, IL2, MMP9) remained positively correlated with immune infiltration, highlighting the dual role of TNF-α in the TME." (PMID 40430573, 2025). "A growing body of research implies that genetic variations in the TNF-α promoter region affect the protein’s translation and ensuing cancer." (PMID 39570546, 2025). "Binding to tumor necrosis factor receptor 1(TNFR1) enables TNF-α to activate pro-inflammatory gene expression and promote cancer progression via pathways such as NF-κB, while also triggering programmed cell death through both apoptosis and necroptosis." (PMID 41000397, 2025).
cancer (continued). "The modulation of TNF-α levels has been shown to correlate with pain intensity in cancer patients, highlighting its potential as a therapeutic target." (PMID 40579593, 2025). "For instance, the production of inflammatory cytokines IL-6 and TNF-α, which play a crucial role in cancer-related inflammation, depends also on TERT binding to NF-κB." (PMID 39858033, 2025). "Epithelial cells undergo abnormal proliferation, while IL-6 and TNF-α activate the inflammation-to-cancer pathway, ultimately driving cellular carcinogenesis." (PMID 41415031, 2025). "Though the effects of TNF-α on cancer cells were studied before and great achievements have been accomplishment, the resolutions of these studies are not high and cannot reach single molecule level." (PMID 41415204, 2025). "Tumor necrosis factor (TNF)-related apoptosis-inducing ligand (TRAIL) is described as selectively inducing cell apoptosis in cancer cells while sparing untransformed cells." (PMID 40429781, 2025). "As well, a reduced enrichment of ‘TNF‐α signalling via NFκB’ was also observed in iCAFs from non‐responders, compared to iCAFs from responders, in pan‐cancer scRNA‐seq landscape of ICI therapy." (PMID 40375605, 2025). "Current data suggest that anti-TNF therapies can be administered safely in IBD patients with a history of cancer, though decisions should be individualized and made in multidisciplinary settings." (PMID 41228267, 2025). "Our results demonstrated that co-culturing of induced THP-1 cells with H101-treated cancer cells produced an increased expression of cytokines, including TNF, IL-12 and IFN-γ." (PMID 40296909, 2025). "Future research should aim to overcome resistance mechanisms, develop personalized therapeutic strategies, and balance the effects of TNF-α in cancer therapy." (PMID 40558596, 2025). "Evidence from RA cohorts offers indirect insight: a recent Japanese registry study found that cancer incidence among TNF inhibitor users was comparable to that of the general population." (PMID 41302997, 2025). "By decreasing IL-6, STAT3, NF-κB, PGE-2, COX-2, and TNF-α levels, combining the effects of prebiotics and probiotics helps lower inflammation and inhibit cancer-promoting pathways, offering a promising strategy for CRC prevention and treatment." (PMID 41322104, 2025). "Although high-dose TNF-α has been utilized as a cytotoxic agent over the past few decades, recent preclinical cancer models support the link between chronic, low-level exposure to TNF-α, and the development of pro-malignant phenotypes." (PMID 39860044, 2025). "The qPCR analysis of the same samples demonstrated that mRNA expression levels of IL‐6, VEGF, IL‐8, and TNF‐α were significantly upregulated in cancer tissues compared to adjacent tissues, with Fold Changes ranging from 2.5 to 4.0 (p < 0.01)." (PMID 40596746, 2025). "Heterogeneity at post-intervention was moderate-to-high for CRP, IL-6, IL-6-CNS, IL-6-cancer, TNF-α, IL-10, IFN-γ, BDNF, and cortisol." (PMID 40281902, 2025). "TNF-α is a pleiotropic cytokine that orchestrates a dual role in cancer progression by modulating both apoptotic and proliferative pathways." (PMID 41000397, 2025). "Enrichment analysis of TCGA data revealed that EAO cancers were downregulated in several pathways involved in immune response, including TNFα signaling and interferon alpha and gamma response." (PMID 39980836, 2025). "This paradox highlights the complexity of TNF-α in the context of malignancy and underscores the need for careful consideration when prescribing TNF-α inhibitors to patients with a history of cancer." (PMID 40227584, 2025). "M1 macrophages polarized by GM-CSF, IFN-γ, TNF-α and LPS are known to enhance proinflammatory and antitumor effect, leading to inflammation or cancer sites via activation of Th1 cell response." (PMID 40050933, 2025).